TANC2 (tetratricopeptide repeat, ankyrin repeat and coiled-coil containing 2)
Description:
Scaffolding protein in the dendritic spines which acts as immobile postsynaptic posts able to recruit KIF1A-driven dense core vesicles to dendritic spines.
Synonyms: KIAA1148; KIAA1636; DKFZP564D166; FLJ10215; FLJ11824; rols; ROLSA; IDDALDS
Tractability: PROTAC: ubiquitination databases record sites on it; its protein half-life has been measured.
Gene: Protein-coding gene on chromosome 17 (62,966,235 to 63,427,703, forward strand). Ensembl gene ENSG00000170921.
Subcellular location: Cell projection, dendritic spine
Subcellular location (Human Protein Atlas): Cytosol
Gene Ontology:
Molecular function: protein binding; structural constituent of postsynaptic density
Biological process: dense core granule cytoskeletal transport; regulation of dendritic spine development; regulation of dendritic spine morphogenesis; maintenance of postsynaptic density structure
Cellular component: dendritic spine; axon
Genetic constraint (gnomAD): Loss-of-function variants: 22 observed, 184.8 expected, observed/expected ratio (o/e) 0.12, 90% interval 0.084 to 0.17. The upper end of that interval is the gene's LOEUF score, 0.17, which puts it in group 1 of 6, group 1 being the genes least tolerant of losing a copy. Missense variants: 2,074 observed, 2,597.2 expected, observed/expected ratio (o/e) 0.8, 90% interval 0.77 to 0.83. Synonymous variants: 910 observed, 969.91 expected, observed/expected ratio (o/e) 0.94, 90% interval 0.89 to 0.99.
Gene-disease validity (ClinGen):
ClinGen rates the evidence that TANC2 causes each of these diseases.
intellectual developmental disorder with autistic features and language delay, with or without seizures (autosomal dominant): Definitive.
Homologues: Orthologues: macaque TANC2 (99% identical), chimpanzee TANC2 (99% identical), rabbit TANC2 (98% identical), rat Tanc2 (98% identical), guinea pig TANC2 (95% identical), dog TANC2 (95% identical), pig TANC2 (95% identical), mouse Tanc2 (94% identical), tropical clawed frog tanc2 (86% identical), zebrafish tanc2a (71% identical), zebrafish tanc2b (68% identical). Paralogues in human: TANC1 (48% identical), CTTNBP2 (12% identical), ANKRD65 (5% identical), ANKRD63 (4% identical).
Diseases named in the same sentence as TANC2 in open-access papers:
TANC2 is named in the same sentence as 31 diseases in open-access papers, as found by Europe PMC text mining. Sharing a sentence is not in itself a finding about the gene and the disease. The quoted sentences say what the papers report.
epilepsy (4 papers, 2021 to 2025). A brain disorder characterized by episodes of abnormally increased neuronal discharge resulting in transient episodes of sensory or motor neurological dysfunction, or psychic dysfunction. "We describe several genes-including CDKL5, TSC1/2, SCN1a, and TANC2-that have been associated with epilepsy, ASD, or other NDD phenotypes that play a critical role in regulating one or more stages of brain development or function but differ widely in their disease-causing mechanisms." (PMID 41594775, 2025). "The TANC2 gene mutations were reported in neurodevelopmental disorders and epilepsy but not in LGS ever." (PMID 34861844, 2021).
Intellectual disability (4 papers, 2015 to 2022). "In humans, TANC2 mutations are extensively associated with various neuropsychiatric disorders, including intellectual disability, ASD, developmental delays, and schizophrenia." (PMID 33976205, 2021). "In humans, TANC2 mutations have been extensively associated with various neurodevelopmental and neuropsychiatric disorders, including intellectual disability, schizophrenia, and ASD23,28–36." (PMID 33976205, 2021). "(For example, a TANC2 variant in a patient with intellectual disability and febrile seizures and in a patient with ASD, and a SMURF1 variant in a patient with epileptic encephalopathy)." (PMID 25763846, 2015). "Expression levels of the TANC gene family genes TANC1 and TANC2 have been indicated to regulate the density of dendritic spines and excitatory synapses and diagnostic exome sequencing identified a de novo TANC1 missense variation in one patient with severe intellectual disability." (PMID 27774450, 2016).
autism (2 papers, 2019 to 2021). Persistent deficits in social interaction and communication and interaction as well as a markedly restricted repertoire of activity and interest as well as repetitive patterns of behavior. "Hub genes of the turquoise module included one GABA receptor encoding genes such as Gabrb1, one glutamate receptor gene (Grid2) and genes tightly associated with synaptic development and autism (Nrxn1, Lrfn5, Plcb1, Erc2, Frmpd4, Tanc2, Ctnnd2, Dmd)." (PMID 34021132, 2021). "In summary, we have demonstrated an excess of de novo disruptive TANC2 mutations among patients with neurodevelopmental delay and autism." (PMID 31616000, 2019).
developmental delay (2 papers, 2016 to 2021). "Exome sequencing of the patient with infantile spasms and developmental delay described here detected heterozygosity for a de novo mutation in the HSPE1 gene and chromosomal microarray analysis detected a de novo deletion affecting the TANC2 gene." (PMID 27774450, 2016).
Obesity (2 papers, 2022 to 2023). Accumulation of substantial excess body fat. "There are no reports of hepatic impairment in patients with autosomal-dominant TANC2 mutation thus far, although at least one patient in this study exhibited obesity with fatty liver." (PMID 34964047, 2022).
Alzheimer disease (1 paper, 2024). A progressive, neurodegenerative disease characterized by loss of function and death of nerve cells in several areas of the brain leading to loss of cognitive function such as memory and language. "Additionally, TANC2 has been identified in a cholesterol homeostasis-related module of Alzheimer’s disease DEG." (PMID 39165421, 2024).
Anxiety (1 paper, 2021). Intense feelings of nervousness, tension, or panic often arise in response to interpersonal stresses. "The synaptic and behavioral phenotypes of Tanc2+/− mice implicate Tanc2 in the regulation of synaptic plasticity and behaviors, including LTP, learning and memory, hyperactivity, and anxiety-like behavior, all of which are reversed by rapamycin-dependent mTOR inhibition." (PMID 33976205, 2021).
autoimmune disease (1 paper, 2023). A disorder resulting from loss of function or tissue destruction of an organ or multiple organs, arising from humoral or cellular immune responses of the individual to their own tissue constituents. "TANC2-derived rno_circRNA_002774 was downregulated in Cyclosporin A-induced cardiotoxicity, which may be a novel therapeutic target in autoimmune diseases and allotransplantation." (PMID 37498303, 2023).
behavioral disorders (1 paper, 2019). "Combined, these observations indicate the important role of TANC2 not only during neurodevelopment but also highlight the later risk of psychiatric or behavioral disorders." (PMID 31616000, 2019). "We define the NDD syndrome as attributed to the loss of TANC2; in addition, our data show that adult patients and carrier parents can present with a more complex series of psychiatric and behavioral disorders." (PMID 31616000, 2019).
breast carcinoma (1 paper, 2021). "To accomplish this, we utilized CRISPR/Cas9-mediated gene editing to engineer the TANC2-PRKCA fusion from the endogenous genes in the MDA-MB-231 breast cancer cell line." (PMID 33617877, 2021).
cardiac hypertrophy (1 paper, 2023). "Six hub genes (TANC2, ADAMTS2, DYNLL1, MRC2, EGR1, and OTUD1) showed anomaly trend in cardiac hypertrophy." (PMID 37498303, 2023). "A total of six hub genes (TANC2, ADAMTS2, DYNLL1, MRC2, EGR1, and OTUD1) were considered cardiac hypertrophy and HF regulators." (PMID 37498303, 2023).
Cognitive impairment (1 paper, 2024). Abnormal cognition is characterized by deficits in thinking, reasoning, or remembering. "Deletion of TANC2 in the hippocampus hyperactivates mTORC1/mTORC2-dependent signaling pathways, leading to cognitive impairment and hyperactivity in mice." (PMID 39524934, 2024).
depression (1 paper, 2021). "Female adult Tanc2+/− mice showed largely similar behavioral abnormalities; hyperactivity (open-field) and anxiolytic-like behavior (elevated plus-maze) but normal depression-like behavior (forced-swim and tail-suspension)." (PMID 33976205, 2021).
liver dysfunction (1 paper, 2022). "Tanc2 disruption was associated with a series of abnormalities emblematic of liver dysfunction." (PMID 34964047, 2022).
low grade glioma (1 paper, 2021). A grade I or grade II glioma arising from the central nervous system. "The 3' fusions TANC2-PRKCA, SLC44A1-PRKCA, and GGA2-PRKCB, found in lung squamous cell carcinoma (LUSC), papillary glioneuronal tumors (PGNT), and low-grade glioma (LGG), respectively, were selected for biochemical analysis." (PMID 33617877, 2021).
lung adenocarcinoma (1 paper, 2022). A carcinoma that arises from the lung and is characterized by the presence of malignant glandular epithelial cells. "Moreover, we also identified several genes with IDR hotspots, which play important roles in cancer, such as FNDC1 in lung adenocarcinoma and TANC2 in uterine corpus endometrial carcinoma." (PMID 35061901, 2022).
multiple sclerosis (1 paper, 2023). A progressive autoimmune disorder affecting the central nervous system resulting in demyelination. "In patients with multiple sclerosis, TANC2 could be engaged in inflammatory and neural repair pathways." (PMID 37498303, 2023).
cancer (3 papers, 2022 to 2025). A tumor composed of atypical neoplastic, often pleomorphic cells that invade other tissues. "The upregulated expression of FNDC1 has been demonstrated to be correlated to poor prognosis in cancer and TANC2 was identified as a driver gene in cancer with effects on cell growth, survival and transformation." (PMID 35061901, 2022).
psychiatric disorder (2 papers, 2019 to 2025). A disorder characterized by behavioral and/or psychological abnormalities, often accompanied by physical symptoms. "In the PFC, decreased expression was observed for Homer1, which plays a crucial role in the postsynaptic density of excitatory synapses, and Tanc2, which helps maintain synaptic structure and function and has been implicated in psychiatric disorders." (PMID 41002437, 2025). "Deciphering the function of TANC2 will undoubtedly provide additional insights with respect to PSD-related pathogenesis and its importance with respect to converging NDDs and psychiatric disorders." (PMID 31616000, 2019).
brain disorder (1 paper, 2021). A disease affecting the brain or part of the brain. "Moreover, Tanc2 modulations promoting or suppressing mTOR signaling have therapeutic potential for the treatment of various mTOR-related peripheral and brain disorders." (PMID 33976205, 2021).
neurologic disorders (1 paper, 2017). "Recently, investigation of patients with diverse neurologic disorders found TANC1 and TANC2 as possible candidate disease genes." (PMID 28754924, 2017).
TANC2 also shares sentences with these, for which no sentence is quoted: neurodevelopmental disorder (3 papers); Epileptic encephalopathy (1); infantile spasms (1); language delay (1); lung squamous cell carcinoma (1); Neurodevelopmental delay (1); papillary glioneuronal tumor (1); schizophrenia (1); thyroid cancer (1); uterine corpus endometrial carcinoma (1).